MT-ND2 (mitochondrially encoded NADH:ubiquinone oxidoreductase core subunit 2)
Description:
Core subunit of the mitochondrial membrane respiratory chain NADH dehydrogenase (Complex I) which catalyzes electron transfer from NADH through the respiratory chain, using ubiquinone as an electron acceptor. Essential for the catalytic activity and assembly of complex I.
Synonyms: ND2; NAD2; formerly MTND2
Tractability: Small molecule: an approved drug acts on it; a structure with a bound ligand is known. Antibody: UniProt predicts a signal peptide or a membrane-spanning region.
Gene: Protein-coding gene on chromosome MT (4,470 to 5,511, forward strand). Ensembl gene ENSG00000198763.
Subcellular location: Mitochondrion inner membrane
Pathways (Reactome):
Metabolism: Complex I biogenesis; Respiratory electron transport
Metabolism of proteins: Mitochondrial protein degradation; Mitochondrial translation termination
Gene Ontology:
Molecular function: NADH dehydrogenase (ubiquinone) activity; protein binding; ionotropic glutamate receptor binding; protein kinase binding
Biological process: mitochondrial electron transport, NADH to ubiquinone; mitochondrial respiratory chain complex I assembly; aerobic respiration; proton motive force-driven mitochondrial ATP synthesis; proton transmembrane transport; response to hypoxia
Cellular component: mitochondrial inner membrane; mitochondrion; respiratory chain complex I
Gene-disease validity (ClinGen):
ClinGen rates the evidence that MT-ND2 causes each of these diseases.
mitochondrial disease (mitochondrial): Moderate.
Leigh syndrome (mitochondrial): Limited. A progressive neurological disease defined by specific neuropathological features associating brainstem and basal ganglia lesions.
Homologues: Orthologues: chimpanzee MT-ND2 (96% identical), macaque ND2 (73% identical), rabbit MT-ND2 (63% identical), pig ND2 (62% identical), guinea pig MT-ND2 (57% identical), mouse mt-Nd2 (57% identical), rat Mt-nd2 (56% identical), tropical clawed frog ND2 (51% identical), zebrafish mt-nd2 (45% identical), Drosophila melanogaster mt:ND2 (34% identical). Paralogues in human: MT-ND5 (21% identical), MT-ND4 (18% identical).
Diseases named in the same sentence as MT-ND2 in open-access papers:
MT-ND2 is named in the same sentence as 84 diseases in open-access papers, as found by Europe PMC text mining. Sharing a sentence is not in itself a finding about the gene and the disease. The quoted sentences say what the papers report.
breast cancer (9 papers, 2011 to 2024). A primary or metastatic malignant neoplasm involving the breast. "Five mitochondrial genes (MT-ND4, MT-ND1, MT-ND3, MT-ND6, and MT-ND2), which were identified as key genes of the complex I biogenesis pathway by Pathformer, were also reported to be associated with breast cancer prognosis." (PMID 38741230, 2024). "Also, the polymorphism of MT-ND2: m.A4769G and m.G5460A are found in breast cancer." (PMID 24414975, 2014). "In a study conducted on a Polish population, a total of 28 changes were detected in MT-ND1, MT-ND2, MT-ND3 and MT-ND6 in breast cancer cells, which were described in databases as polymorphisms." (PMID 37189801, 2023). "A subset of genetic variations in complex I and IV genes, MT-ND2 and MT-COII, has recently been related to breast cancer risk of European Americans in 2,723 breast cancer cases and 3,260 controls from a Multiethnic Cohort Study." (PMID 36119536, 2022). "In one of the studies conducted in a Polish population, involving mutations and polymorphisms within the MT-ND1, MT-ND-2, MT-ND3, and MT-ND6 genes in breast cancer cells, there were 28 polymorphisms, mostly located within the MT-ND-2 gene, that were absent from healthy cells." (PMID 34065857, 2021).
Parkinson disease (8 papers, 2006 to 2025). A progressive degenerative disorder of the central nervous system characterized by loss of dopamine producing neurons in the substantia nigra and the presence of Lewy bodies in the substantia nigra and locus coeruleus. "In humans, variants in the MT-ND2 gene, particularly m.5178C>A, exhibit a link with longevity as well as lipid metabolism and the incidence of age-related diseases, e.g., Parkinson’s disease." (PMID 31337008, 2019).
COVID-19 (6 papers, 2021 to 2025). A disease caused by infection with severe acute respiratory syndrome coronavirus 2. "In influenza, UBE2S, USP53, and TIMM10 were observed in this category, while in COVID-19, UBE2T, UBE2C, DTL, MT-ND2, UCHL1, and UBA52 were implicated." (PMID 41020849, 2025). "By comparing the upregulated genes between COVID-19 patients and recovered individuals, we found that 21 genes (i.e., RPL4, MT-ND2, SCD5, MT-CYB, EZR) were shared between the conditions." (PMID 36059456, 2022).
Obesity (6 papers, 2014 to 2022). Accumulation of substantial excess body fat. "Additive interactions (epistasis) between mitochondrial variants in the MT-ND2 gene and nuclear variants in genes responsible for mitochondrial replication and transcription have been demonstrated to influence the BMI and obesity phenotype." (PMID 35328073, 2022). "The missense variant MT:5460G > A (Ala331Thr) in the MT-ND2 gene showed the most significant correlation (P = 0.009) and was associated with a threefold increased risk of obesity." (PMID 33659027, 2021). "The missense variant MT:5460G > A from the MT-ND2 gene was only positively correlated with obesity." (PMID 33659027, 2021). "What is more, we show that genetic epistasis might influence obesity phenotype by interaction of variants in MT-ND2 gene with nuclear variants in genes responsible for mitochondrial replication and transcription." (PMID 32635923, 2020). "In this study we have considered the heteroplasmy effect and found mtSNPs in candidate gene regions to be significantly associated with BMI that previously were suggested to be implicated in obesity, body fat mass, or intramuscular fat (MT-ND1, MT-ND2, and MT-CO1)." (PMID 25153900, 2014).
Hypertension (5 papers, 2009 to 2024). The presence of chronic increased pressure in the systemic arterial system. "The MT-ND2-rs3020602 variant was associated with hypertension in the diabetic cohort." (PMID 39258111, 2024).
colon cancer (4 papers, 2015 to 2024). "While we did not genotype this mtSNP, which is located close to the MT-ND2 gene (145 base pair distance), we did observe an association between the MT-ND2 gene and colon tumors (P = 7.0x10–4), which may support the reported association." (PMID 26340450, 2015). "In addition, an association between the MT-ND2 gene and CRC risk was observed among European Americans with stronger association seen in colon tumors." (PMID 26340450, 2015).
diabetes (4 papers, 2019 to 2024). "Lastly, to investigate whether the lifespan-linked mt-Nd2 mutation also contributes to other age-related phenotypes, we induced a diet-induced diabetes model in the female B6-mtALR and B6-mtBPL mice." (PMID 31337008, 2019). "In addition, the mitochondrial gene NADH dehydrogenase 2 (mt-ND2), a T1D-associated SNP, demonstrates a resistant allele that prevents diabetes in NOD mice, a model of T1D, following adoptive transfer of diabetogenic T-cells, and reduces T-cell mediated killing of a β-cell line in vitro." (PMID 38404962, 2024). "Since the ALD-linked Chr 8 locus overlaps with T1D-protective Idd22, and mt-Nd2a was also associated with T1D, the interaction between mt-Nd2 and Chr 8 appears to regulate β-cell survival during development of diabetes." (PMID 36276935, 2022). "The ALR genome provided diabetes resistance at both mt-Nd2 and a defined region on Chr 8 that has an overlapping confidence interval with Idd22." (PMID 36276935, 2022).
Anxiety (3 papers, 2015 to 2025). Intense feelings of nervousness, tension, or panic often arise in response to interpersonal stresses. "We further identified several significant mtDNA×CRP associations for anxiety and depression, including mitochondrial gene MT-ND2 for PHQ-9 and MT-CYB for self-reported depression, MT-ND1 for self-reported anxiety, MT-CO3 for GAD score." (PMID 37344456, 2023). "Since the important role of ROS in depression and anxiety, as well as the associations between ROS and inflammatory, based on these phenomena, it is plausible that the interaction between MT-ND1 and MT-ND2 and CRP may occur by acting on ROS for mood disorders." (PMID 37344456, 2023). "In addition, 4 mtDNA variants were detected to interact with CRP for both anxiety and depression, including m.12633C>A(MT-ND5), m.9899T>C(MT-CO3), m.4561T>C(MT-ND2), m.11377G>A(MT-ND4)." (PMID 37344456, 2023). "There were 5 common mtDNAs shared with anxiety and depression in MiWAS, namely m.10915T>C(MT-ND4), m.3010G>A(MT-RNR2), m.9899T>C(MT-CO3), m.15257G>A(MT-CYB) and m.4580G>A(MT-ND2)." (PMID 37344456, 2023).
glaucoma (3 papers, 2013 to 2023). Increased pressure in the eyeball due to obstruction of the outflow of aqueous humor. "Haplogroup U and rare variants in the mitochondrial DNA-encoded MT-ND2 gene may be protective against primary open-angle glaucoma." (PMID 30242360, 2018).
ischemia (3 papers, 2022 to 2025). A hypoperfusion of the BLOOD through an organ or tissue caused by a PATHOLOGIC CONSTRICTION or obstruction of its BLOOD VESSELS, or an absence of BLOOD CIRCULATION. "Only a few changes in the mitochondrial proteome were found following ischemia; these were the down-regulation of the TCA cycle enzymes DLD and SUCLA2 and the ETC members MT-ND2 and ATP5A1." (PMID 35216205, 2022).
age-related macular degeneration (2 papers, 2008 to 2014). Age-related loss of vision in the central portion of the retina (macula), secondary to retinal degeneration. "The objective of this study was to determine if MTND2*LHON4917G (4917G), a specific non-synonymous polymorphism in the mitochondrial genome previously associated with neurodegenerative phenotypes, is associated with increased risk for age-related macular degeneration (AMD)." (PMID 18461138, 2008).
Alzheimer disease (2 papers, 2017 to 2018). A progressive, neurodegenerative disease characterized by loss of function and death of nerve cells in several areas of the brain leading to loss of cognitive function such as memory and language. "For instance, MT-ND1 and MT-ND2 harbor additional nsSNPs at the interface that are also linked to other diseases, such as Alzheimer's disease (MIM 502500) and MELAS syndrome (MIM 540000)." (PMID 28841721, 2017).
atherosclerosis (2 papers, 2012 to 2015). A disease characterized by the build-up of fatty material and calcium deposition in the arterial wall resulting in partial or complete occlusion of the arterial lumen. "Thus, it was demonstrated that at least five mitochondrial mutations occurring in MT-RNR1, MT-TL1, MT-ND2, MT-ND5, and MT-CYB genes are associated with atherosclerosis." (PMID 22997526, 2012).
Sepsis (2 papers, 2018 to 2023). Sepsis is defined as life-threatening organ dysfunction caused by a dysregulated host response to infection. "In addition, the expression of Mt-Nd1 and Mt-Nd2 normalized to the nuclear Ppia were similar in the SF and SPF groups, but lower in the Sepsis group than in the SPF group (p < 0.05), indicating that sepsis induced mt DNA depletion." (PMID 37106730, 2023).
breast tumours (1 paper, 2014). "The purpose of this study was to analyze mutations in MT-ND1, MT-ND2, MT-ND3 and MT-ND6 genes and their effect on the biochemical properties, structure and functioning of proteins in patients with breast tumours." (PMID 24414975, 2014).
colorectal tumor (1 paper, 2015). "Future studies should examine the expression of MT-ND2 in colorectal tumor and test mitochondrial genes encoded by both the nuclear and mitochondrial genomes to fully examine their contribution to CRC risk." (PMID 26340450, 2015).
hepatocellular carcinoma (1 paper, 2025). A malignant tumor that arises from hepatocytes. "Furthermore, the cellular expression of DEGs from eosinophils such as IFITM1 and S100A9 was associated with the progression of inflammatory‐mediated disease‐driven hepatocellular carcinoma via upregulated mitochondrial oxidative phosphorylation genes (MT‐ND1 and MT‐ND2)." (PMID 41190282, 2025).
invasive ductal carcinoma (1 paper, 2023). "Interestingly several variants were observed exclusively in patients with invasive ductal carcinoma (NST/NOS) and these included a missense variant each in MT-ND1 (A3434G), MT-ND2 (G4491A), MT-TD (T7581C), MT-CO2 (G7859A), MT-ND3 (G10143A)." (PMID 36758048, 2023).
macular degeneration (1 paper, 2025). Loss of vision in the central portion of the retina (macula), secondary to retinal degeneration. "The A4917G mutation in MT-ND2, when present homoplasmically, has been associated with an increased risk of macular degeneration due to mitochondrial dysfunction in a study conducted on Caucasian populations." (PMID 40053230, 2025).
type 1 diabetes (1 paper, 2024). "Mt-Nd2 is crucial for controlling the production of ROS, and single-nucleotide polymorphisms in Mt-Nd2 suppress ROS production and type 1 diabetes development." (PMID 39795876, 2024).
tumor (29 papers, 2009 to 2026). "OSCC cells exhibited strong upregulation of COX-2 and mitochondrial genes (MT-ND2, MT-ND4, MT-ND5, and cytochrome b), indicating increased metabolic activity, a hallmark of tumor progression." (PMID 40061903, 2025). "The direct RNA targets of miR-24 include mitochondrial mt-Nd2 and Snora75, and their targeting leads to mitochondrial dysfunction and growth inhibition in tumour cells." (PMID 39183323, 2024). "Platelets inhibit tumor growth by transporting mir-24 to cancer cells targeting mt-Nd2 and Snora75, indicating that the regulatory effect of platelets on tumor growth is diverse." (PMID 39720182, 2024). "In this analysis, we observed a statistically significant difference between all groups, with tumor group presenting more heteroplasmic variants in MT-RNR1, MT-ND5, MT-ND4, MT-ND2, MT-DLOOP1 and MT-CO1." (PMID 31673122, 2019). "On the other hand, miR-24, another miRNA which is transferred from platelet MPs to tumor cells, constrains tumor growth by targeting mitochondrial mt-Nd2, and Snora75, resulting in mitochondrial dysfunction and tumor suppression." (PMID 30791448, 2019). "Further, the higher rate of heteroplasmic variants in tumor groups was statistically significant in six of such regions: MT-RNR1, MT-ND5, MT-ND4, MT-ND2, MT-DLOOP1 and MT-CO1." (PMID 31673122, 2019). "Tumor also presented substantially more variants in the following regions: MT-RNR1, MT-ND5, MT-ND4, MT-ND2, MT-DLOOP1 and MT-CO1." (PMID 31673122, 2019). "The inhibition of mt-Nd2 and Snora75 resulted in mitochondrial dysfunction and growth inhibition of tumor cells." (PMID 29670887, 2018). "However, some studies have indicated that certain natural PEVs can potentially affect tumour growth, such as PEVs that inhibit mitochondrial mt-ND2 and Snora75 (a non-coding small nucleolar RNA) by transferring miR-24, resulting in mitochondrial dysfunction and tumour cell growth inhibition." (PMID 39183323, 2024). "Particularly, at the single-site level, three CpG positions were significantly hypermethylated in tumors relative to matched non-tumor samples, two located within MT-ATP6 gene and one in the short intergenic region between MT-ND2 and MT-CO1 genes." (PMID 41602822, 2026). "Moreover, the RT-PCR of tumor tissues showed that mRNA level of ACO2, ATP5B, and MT-ND2 were lower in CRS + Lv-ALDH3A1 than those in CRS + NC group." (PMID 38191346, 2024). "Additionally, the silent somatic m.5147G>A in MT-ND2 was found in the II.4 tumor tissue, which is highly unlikely to be pathogenic despite its high heteroplasmy." (PMID 34831144, 2021).
cancer (17 papers, 2015 to 2025). A tumor composed of atypical neoplastic, often pleomorphic cells that invade other tissues. "These mitochondrial genes included MT-CO1, MT-CO2, MT-CO3, MT-ATP6 and 8, and MT-ND2,3,4,5, and 6 (left), which are critical for energy production and cancer cell survival and likely important for thwarting of therapy effectiveness observed in these FOXM1 inhibitor-resistant cells." (PMID 34944900, 2021). "Moreover, ND2 protein expression was higher in cancer tissues compared to adjacent normal tissues, suggesting that D-loop methylation levels may play a role in regulating MT-ND2 expression." (PMID 33925624, 2021). "Only MT-ND2 and PDGFRA were consistently downregulated across all five cancer types." (PMID 39594421, 2024). "Also among the upregulated genes were mitochondrial protein coding genes (MT-ND3, MT-ND4L, MT-ND4, MT-ND2, MT-CYB, MT-ND1, MT-CO1 etc), which may be as a result of the elevated metabolism characteristic of cancer cells to sustain their survival." (PMID 29132323, 2017).
MT-ND2 also shares sentences with these, for which no sentence is quoted: medulloblastoma (8 papers); Leigh syndrome (6); mitochondrial disease (5); infection (4); myocardial infarction (4); colorectal cancer (3); dyslipidemia (3); amyotrophic lateral sclerosis (2); epilepsy (2); Huntington disease (2); Leber hereditary optic neuropathy (2); leprosy (2); leukemia (2); pancreatic cancer (2); acute myeloid leukaemia (1); age (1); aplastic anemia (1); asthenozoospermia (1); autism (1); bipolar disorder (1); cardiac diseases (1); cardiomyopathy (1); cardiovascular disease (1); cyst (1); dengue (1); depression (1); energy metabolism disorder (1); esophageal cancer (1); essential hypertension (1); familial focal epilepsy (1).
A further 32 diseases each share a sentence with MT-ND2 in 1 paper.